UNC79 (unc-79 subunit of NALCN channel complex)
Description:
Auxilary subunit of the NALCN channelosome complex, which regulates the resting membrane potential by depolarizing sodium leak currents. The NALCN channelosome complex is a voltage-gated ion channel responsible for the resting Na(+) permeability that controls neuronal excitability. The NALCN channelosome is constitutively active and conducts monovalent cations but is blocked by physiological concentrations of extracellular divalent cations. Activated by neuropeptides substance P, neurotensin, and extracellular Ca(2+) that regulates neuronal excitability by controlling the sizes of NALCN-dependent sodium-leak current (By similarity).
Synonyms: KIAA1409
Tractability: Small molecule: a structure with a bound ligand is known. Antibody: UniProt places it where antibodies can reach, with high confidence; its Gene Ontology location is reachable by antibodies, with high confidence; UniProt predicts a signal peptide or a membrane-spanning region; the Human Protein Atlas places it where antibodies can reach.
Gene: Protein-coding gene on chromosome 14 (93,333,219 to 93,707,876, forward strand). Ensembl gene ENSG00000133958.
Subcellular location: Cell membrane
Subcellular location (Human Protein Atlas): Plasma membrane; Nucleoplasm
Pathways (Reactome):
Transport of small molecules: Stimuli-sensing channels
Gene Ontology:
Biological process: regulation of neuronal action potential; sodium ion transmembrane transport
Cellular component: plasma membrane; voltage-gated sodium channel complex
Genetic constraint (gnomAD): Loss-of-function variants: 35 observed, 276.87 expected, observed/expected ratio (o/e) 0.13, 90% interval 0.096 to 0.17. The upper end of that interval is the gene's LOEUF score, 0.17, which puts it in group 1 of 6, group 1 being the genes least tolerant of losing a copy. Missense variants: 2,219 observed, 3,277.5 expected, observed/expected ratio (o/e) 0.68, 90% interval 0.65 to 0.7. Synonymous variants: 1,087 observed, 1,236.1 expected, observed/expected ratio (o/e) 0.88, 90% interval 0.84 to 0.93.
Homologues: Orthologues: chimpanzee UNC79 (97% identical), pig UNC79 (95% identical), dog UNC79 (95% identical), rat Unc79 (95% identical), mouse Unc79 (94% identical), guinea pig UNC79 (91% identical), macaque UNC79 (90% identical), tropical clawed frog unc79 (87% identical), Drosophila melanogaster unc79 (33% identical), Caenorhabditis elegans unc-79 (25% identical).
Diseases named in the same sentence as UNC79 in open-access papers:
UNC79 is named in the same sentence as 22 diseases in open-access papers, as found by Europe PMC text mining. Sharing a sentence is not in itself a finding about the gene and the disease. The quoted sentences say what the papers report.
Alzheimer disease (2 papers, 2014 to 2020). A progressive, neurodegenerative disease characterized by loss of function and death of nerve cells in several areas of the brain leading to loss of cognitive function such as memory and language. "Both GRIK1 and UNC79 are involved in ion transmembrane transport and were not prioritised as likely causal genes in a recent GWAS of Alzheimer’s disease, highlighting the potential utility of FOCUS in gene prioritisation." (PMID 32299494, 2020). "In addition, genes encoding NALCN, NLF- 1, UNC-79, and UNC-80 proteins may be susceptibility loci for several diseases including bipolar disorder, schizophrenia, Alzheimer's disease, autism, epilepsy, alcoholism, cardiac diseases and cancer." (PMID 24904279, 2014).
lung adenocarcinoma (1 paper, 2023). A carcinoma that arises from the lung and is characterized by the presence of malignant glandular epithelial cells. "Among the DEGs involved in BM, UNC79 was the most highly expressed gene in the lung adenocarcinoma tissues from the BM group." (PMID 37139160, 2023).
neuropathic pain (1 paper, 2024). Chronic pain caused by damage to nerve fibers. "A recent study shows that the NALCN channel contributes to neuronal sensitization in neuropathic pain, and this result may lead experimental research to examine the regulatory mechanisms of NALCN by UNC79 and their associations with neuropathic pain in detail." (PMID 39526039, 2024).
cancer (3 papers, 2014 to 2024). A tumor composed of atypical neoplastic, often pleomorphic cells that invade other tissues. "UNC79 genes encoding UNC-79 proteins may be susceptibility loci for several diseases including cancer." (PMID 39834937, 2024). "There is no research on the association between UNC79 mutations and cancers." (PMID 37760246, 2023). "The function of three genes (UNC79, PLEKHG4B, and ENSCAFG00845007156) and their associations with cancers have not been clearly identified." (PMID 37760246, 2023). "However, the functions of UNC79, PLEKHG4, and ENSCAFG00845007156 and their associations with cancers have not yet been identified." (PMID 37760246, 2023).
neurodevelopmental disorder (1 paper, 2025). A behavioral and cognitive disorder with onset during the developmental period that involves impaired or aberrant development of intellectual, motor, or social functions. "The Ph subtype significantly expressed UNC79 associated with neurodevelopmental disorder." (PMID 41246237, 2025).
UNC79 also shares sentences with these, for which no sentence is quoted: tumor (3 papers); autism (2); schizophrenia (2); adenocarcinoma (1); alcoholism (1); bipolar disorder (1); cardiac diseases (1); cardiovascular diseases (1); colon adenoma (1); colon cancers (1); colorectal adenoma (1); epilepsy (1); epithelial ovarian cancer (1); Intellectual disability (1); lung carcinoma (1); melanoma (1); ovary cancer (1).